MPO (myeloperoxidase)
Diseases named in the same sentence as MPO in open-access papers (continued):
Sharing a sentence is not in itself a finding about the gene and the disease.
pneumonia (continued). "The significant increase of MPO activity that we found in infants with pneumonia supports this hypothesis." (PMID 25551219, 2014). "Rapidly developing pneumonia can be monitored exactly by several hallmarks of infection and animal well-being, including body weight and clinical score, bacterial load, the granulocyte marker myeloperoxidase (MPO), and levels of key cytokines in the infected organ." (PMID 34451996, 2021). "Therefore, the activity of MPO requires further study depending on the etiology of pneumonia." (PMID 33014465, 2020). "Neutrophil killing of S. pneumonia is mediated through myeloperoxidase, an enzyme that generates reactive oxygen species which, given the increased sensitivity of A-T cells to oxidative damage, could lead to exacerbated tissue damage including that of the lung in patients." (PMID 30796268, 2019). "Especially, MPO, NE and PR3 raised more severely in patients with pneumonia comparing to the patients with mild symptoms." (PMID 40315230, 2025). "Myeloperoxidase (MPO) activity, as a marker of lung inflammation, was 1322 (531–2821) mU/ml of Epithelial Lining Fluid (ELF) and 371(174–1080) mU/ml ELF in infants with pneumonia and in controls, p = 0.047." (PMID 25551219, 2014). "The top 50 over-abundant transcripts in pneumonia were dominated by antimicrobial neutrophil-related genes e.g ELANE, DEFA1B, MMP8, CAMP, DEFA3, DEFA4, MPO, LTF." (PMID 23940611, 2013). "In addition, neutrophil-derived myeloperoxidase (MPO) serves as a potent tissue damage factor and also contributes to influenza pneumonia in mice infected with influenza virus." (PMID 32326602, 2020). "In addition, significant increase was observed in the TNF-α, IL-6, IL-1β, and MPO in the BALF and lung tissue samples collected from the KP-infected pneumonia mice, which were reversed by anemoside B4." (PMID 32625244, 2020). "MPO activity was significantly higher in the tracheal aspirates of newborns with pneumonia compared to those with no lung disease (1322 (531–2821) mU/ml ELF and 371 (174–1080) mU/ml ELF, p = 0.047, respectively)." (PMID 25551219, 2014). "Globally, the lungs were modestly impacted by MRSA, with mild pneumonia and increased MPO activity, but without differences in wet to dry ratio." (PMID 24204769, 2013). "In addition, myeloperoxidase (MPO), an enzyme secreted by leukocytes, is present in myeloid cells, which catalyzes the formation of a variety of active oxidants during the occurrence and development of pneumonia." (PMID 32625244, 2020). "The fact that there was no increase in whole lobe MPO in our model would be consistent with inflammation predominantly confined to intra/peri-bronchial regions rather than inducing a significant parenchymal/pneumonia-like infection." (PMID 27804985, 2016). "Subsequently, we found that the increased activity of MPO in the P. aeruginosa-induced pneumonia group was significantly reduced after the post-treatment of 4-PG groups at 6 and 12 h, while the post-treatment group at 18 h showed no significant changes in MPO concentration." (PMID 30425781, 2018).
Insulin resistance (39 papers, 2008 to 2025). Increased resistance towards insulin, that is, diminished effectiveness of insulin in reducing blood glucose levels. "The co-presence of insulin resistance is associated with increased MPO activity and ROS production, potentiating leukocyte-endothelium interactions." (PMID 37569455, 2023). "In mice, NE, PR3 and CTSG were associated with increased steatosis, inflammation, and insulin resistance, while MPO promoted the development of fibrosis through the activation of hepatic stellate cells." (PMID 35039631, 2022). "In addition, neutrophil-derived NE and MPO are linked to both the induction of insulin resistance and the release of NETs." (PMID 27701440, 2016). "The administration of HCD in piglets has been associated with hepatic steatosis, insulin resistance, and hepatic inflammation, including increased myeloperoxidase activity and expression of proinflammatory cytokines and chemokines, particularly IL-2, CXCL2, TNFα, and IL-6." (PMID 23565157, 2013). "Moreover, we analyzed effect modification by clinical characteristics associated with insulin resistance such as body mass index (BMI), glycosylated hemoglobin A1c (HbA1c), and adiponectin and by daily myeloperoxidase (MPO) level." (PMID 19079718, 2008). "Therefore, mice with NE deficiency or MPO deficiency have reduced adipose tissue inflammation and improved carbohydrate metabolism, including improved glucose tolerance and insulin sensitivity and a reduction in insulin resistance." (PMID 35039631, 2022). "In a different study, myeloperoxidase (MPO), an enzyme released by WBC in inflammatory sites, and ROS production were assessed in PCOS-associated IR and non-insulin-resistant PCOS patients, with elevated levels being observed in women with PCOS-associated IR." (PMID 40650016, 2025). "Specifically, REST upregulates MPO, which was shown to increase the expression of genes involved in gluconeogenesis in hepatocyte cell lines (G6pc) and adipocytes (Pck1) and to induce insulin resistance in adipocytes, preadipocytes, and myotubes." (PMID 37934800, 2024). "The increase in circulating FFA, together with SARS-CoV-2-induced GP73 production, metabolic factors such as MPO, activation of phosphoenolpyruvate carboxykinase, and hyperinsulinemia in response to insulin resistance, stimulate hepatic gluconeogenesis." (PMID 37934800, 2024). "These granulocytes are involved in the induction of insulin resistance via secretion of their granule proteins Neutrophil Elastase (NE) and myeloperoxidase (MPO)." (PMID 27701440, 2016). "Recently, the importance of neutrophils and neutrophil-derived myeloperoxidase and neutrophil elastase on the induction of insulin resistance has been established." (PMID 27701440, 2016). "Inflammatory factors such as adhesion molecules (ICAM-1 and VCAM-1), CD40 ligands, C-reactive protein (CRP) and myeloperoxidase (MPO) participate in induction of insulin resistance and atherosclerotic disease." (PMID 21247435, 2011). "These and other proteins (i.e. ASP, MPO, PAI-1 and VEGF) included in this cluster and in cluster 1 that was associated with insulin were previously found to be increased in subjects with insulin resistance, CVD, or both." (PMID 21203453, 2010). "We hypothesized that young subjects with insulin resistance have high levels of oxidized LDL and HDL associated with a high-fat diet, high myeloperoxidase levels, and a low PON1 concentration." (PMID 39599716, 2024). "Interestingly, MPO is related to insulin resistance and inflammation in overweight individuals with first-degree relatives suffering from T2DM, increasing the risk of developing this disease in these subjects." (PMID 37569455, 2023). "Furthermore, we found that the secreted factors, myeloperoxidase was upregulated whereas apelin and myostatin were downregulated upon SARS-CoV-2 infection, which was potentially linked to the onset of insulin resistance." (PMID 34916489, 2021).
Insulin resistance (continued). "A positive correlation among MPO, insulin resistance and metabolic disorder has been suggested." (PMID 29382883, 2018). "NE was suggested to induce insulin resistance by degradation of insulin receptor substrate 1 and enhancing leukocyte influx involving toll like receptor 4 signaling, while MPO reduces expression of insulin receptor β and enhances chemokine expression resulting in influx of inflammatory cells." (PMID 27701440, 2016). "For example, myeloperoxidase can directly damage oxidised tissues; Elastase participates in the maturation induction of IL-1 and induces the inflammatory cascade reaction, which directly damages the histiocytes and mediates the occurrence of insulin resistance." (PMID 41281289, 2025). "As already discussed (Section 3), palmitate induces insulin resistance in insulin-responsive cells independently of neutrophils, but the latter are recruited to adipose tissue and promote diet-induced insulin resistance by producing myeloperoxidase and other proinflammatory substances." (PMID 29081894, 2017). "Since neutrophil-derived NE and MPO are both connected to the induction of insulin resistance as well as release of NETs, we here hypothesized that NETosis links early neutrophil influx with AT inflammation by stimulating inflammation and mediating leukocyte influx." (PMID 27701440, 2016). "In this sense, it has been shown that pharmacological inhibition of MPO prevented and reversed HFD‐induced insulin resistance in male mice." (PMID 41292131, 2025). "Within adipose tissue, neutrophils secrete NE and MPO, and in mouse models of T2DM, these factors are thought to promote the development of insulin resistance and inflammation in adipose tissue." (PMID 35039631, 2022). "Multivariable adjustment included insulin resistance (IR), smoking, anti-psychotic treatment (DDD), age, sex, BMI, hs-CRP (CRP), and MPO." (PMID 32754070, 2020). "Thus, this study aimed to analyze the relationship between serum levels of oxidized lipoproteins and diet, lipid profiles, and MPO and PON1 levels in young subjects with insulin resistance." (PMID 39599716, 2024). "Furthermore, the inhibition of MPO activity in the neutrophils via a non-specific peroxidase inhibitor decreased diet-induced insulin resistance in obese wild-type mice." (PMID 32277104, 2020). "These ameliorative effects could be related to the improvement of insulin resistance, suppression of oxidative stress and inflammation through mitigation of LPO, restoration of anti-oxidant enzymes (activity & mRNA), and the decreased TNF-α mRNA level and MPO activity." (PMID 32695286, 2020).
mastitis (39 papers, 2016 to 2025). Inflammation of breast tissue during lactation or postpartum due to an obstructed duct or infection. "Nevertheless, the increased levels of ILs and MPO activity during LPS-induced mastitis reflect neutrophil infiltration in the mammary tissues." (PMID 41148692, 2025). "In dairy cows, elevated MPO levels in milk neutrophils and macrophages have been reported in mastitis cow than the healthy one, reflecting its involvement in intramammary infections." (PMID 41252605, 2025). "The literature suggests various immunoassay tests for early inflammation screening utilizing biomarkers like milk amyloid A, cathelicidins, myeloperoxidase enzyme of milk neutrophils, IL-6 as well as lateral flow assays for diagnosing mastitis." (PMID 38787275, 2024). "Consistent with the results of H&E staining, mammary glands CD45 and MPO-positive cells were also significantly increased in the mastitis group." (PMID 37125159, 2023). "For example, ELISA and lateral flow have been developed for the early detection of the enzyme myeloperoxidase of milk neutrophils, a biomarker for subclinical mastitis." (PMID 35804578, 2022). "ATF can reduce MPO activity in mammary tissue of mastitis mice, and it can reduce the aggregation of neutrophils to alleviate LPS-induced inflammation in the mammary gland of mice." (PMID 36090098, 2022). "Consistent with our findings, oral supplementation with β-glucans reduced inflammatory cytokines, MPO, and iNOS levels following LPS-induced mastitis in a previous study in rats." (PMID 36605196, 2022). "The principal findings are as follows FOR significantly inhibited infiltration of neutrophils, inflammatory cytokine production, and MPO activity in LPS-induced mastitis in mice." (PMID 35185907, 2022). "The MPO results showed that the level of myeloperoxidase (MPO) in the mastitis tissue was significantly higher than that in the control group (p < 0.01)." (PMID 36355118, 2022). "MPO activity is a typical sign of inflammatory cell infiltration, so it is widely used to assess the condition of mastitis." (PMID 34858427, 2021). "In an S. aureus-induced mouse mastitis model, histopathology and MPO results revealed that scFvs ameliorated the histopathological damages and reduced the infiltration of inflammatory cells (p < 0.05)." (PMID 35008761, 2021). "We found that gut dysbiotic mice had obvious mastitis features, including increased acinus damage, histological score, MPO activity and pro-inflammatory tumor necrosis factor (TNF)-α and IL-1β expression compared with the control mice." (PMID 34297785, 2021). "MPO activity was used as a biomarker for the infiltration of neutrophils and macrophages, which plays important roles in evaluating the development of mastitis." (PMID 32851026, 2020). "Additionally, a recent study found that levels of IL-6, IL-1β, TNF-α, and MPO were all increased in mice that developed mastitis due to S. aureus." (PMID 41148692, 2025). "However, it has been reported that Lactobacillus plantarum KLDS 1.0344 enhances lactic acid bacteria and reduces MPO activity, thereby mitigating mastitis." (PMID 39199398, 2024). "Kaempferol suppressed phosphorylation of the NF-κB p65 subunit and the degradation of its inhibitor, IκBα, in the NF-κB signal pathway for the treatment of mastitis; this was accompanied by decreased myeloperoxidase (MPO) production and ANGPTL2 expression, as well as a reduction in TNF-α and IL-6." (PMID 38630770, 2024). "Furthermore, it has been documented that diosmetin relieved S. aureus-induced mastitis in mice by inhibiting the expression of MPO, TNF-α, IL-1β, and NF-κB." (PMID 39199398, 2024). "Furthermore, in vivo tests indicated that intramammary infusion of L. casei 03 relieved pathological changes, reduced the secretion of IL1β, IL6 and TNFα and MPO activity in the mouse mastitis model." (PMID 38395896, 2024).
mastitis (continued). "Likewise, dose-dependent decreases in several inflammatory markers during mastitis, including MPO activity, and TNF-α and IL-1β, were detected after HEX treatment compared with S. aureus treatment." (PMID 37948460, 2023). "MPO activity and secretion of pro-inflammatory factors were significantly higher in the MC group than in the NT group, further indicating that the model of LPS-induced mastitis in mice was successfully established." (PMID 36090098, 2022). "We showed that E. coli treatment increased the mastitis inflammation score, MPO activity and consistent expression of cytokines compared to the control group, while Ficz pretreatment decreased the E. coli-induced inflammatory profiles compared to the E. coli treatment." (PMID 34297785, 2021). "Our research results showed that PE could significantly inhibit the increase in the levels of inflammatory mediators such as TNF-α, IL-6, IL-1β, MPO and iNOS during mastitis." (PMID 34383710, 2021). "In this experiment, MPO activity was significantly lower in the peiminine groups, which means that the neutrophil inflammatory infiltration decreased, indicating that peiminine had a certain therapeutic effect on mastitis." (PMID 30200569, 2018). "In addition, peiminine significantly reduced the MPO activity in mice with LPS-induced mastitis (p < 0.0001)." (PMID 30200569, 2018). "Moreover, we found that the SRMT group had several increases in mastitis parameters, including MPO activity, TNF-α, and IL-1β levels, compared with the control and HRMT groups; however, zanamivir treatment alleviated these increases compared with those of the SRMT group." (PMID 37069691, 2023). "In other experimental studies involving mice and rats, during mastitis-induced episodes, increased levels of IL-1β, IL-6, TNF-α cytokines, and MPO were observed (see Section 4)." (PMID 41148692, 2025). "In the K. pneumoniae-induced mouse mastitis model, W. cibaria SDS2.1 significantly reduced myeloperoxidase (MPO) activity, mammary tissue damage, and the expression of inflammatory cytokines (IL-6, IL-1β, and TNF-α) (p < 0.05)." (PMID 40281973, 2025). "Our results demonstrate that ARWD significantly reduced MPO and LDH activities in mastitis models while elevating SOD levels and reducing MDA concentrations." (PMID 40901059, 2025). "Curcumin reduced inflammation, MPO, cytokines, TLR4 expression and NF-κB activation in LPS-induced mastitis model." (PMID 38377032, 2024). "The pathology of mammary gland, MPO activity and inflammatory cytokine production were detected to evaluate the effects of PCA on mastitis." (PMID 37328960, 2023). "Intraperitoneal injection of 10 mg/kg of stephanine can reduce myeloperoxidase (MPO) activity and contents of TNF-α, IL-1β, and IL-6 in the mammary gland tissue of mastitis rats induced by LPS." (PMID 32256634, 2020). "The identification of MPO among candidate genes in our study suggests that variation in this gene may influence SCS and susceptabilty to mastitis." (PMID 41252605, 2025). "Also, in an LPS-induced mouse mastitis model and in LPS-treated mouse mammary epithelial cells, GLY treatment significantly reduced MPO activity and protein expression of TNF-α, IL-1β, and IL-6." (PMID 27792814, 2016). "When studying the effectiveness of SMP against mastitis, it was found that SMP supplementation could inhibit the activities of myeloperoxidase (MPO) and N-acetyl-β-D-glucosaminidase (NAGase) and reduce the expression of IL-6, IL-1β and TNF-α inflammatory factors in rats with mastitis." (PMID 36937857, 2023). "This study found that farrerol could improve pathological injury of mammary glands, attenuate the activity of MPO, inhibit the production of pro-inflammatory mediators (TNF-α, IL-6, IL-1β, iNOS and COX-2) and the phosphorylation of AKT, NF-κB p65, p38 and ERK1/2 in LPS-induced mouse mastitis." (PMID 29904013, 2018).
mastitis (continued). "Pretreatment with DCA intraperitoneally, but not CA, alleviated S. aureus-induced mastitis, as evidenced by DCA improving mammary injury, mammary S. aureus burden, proinflammatory markers including TNF-α, IL-1β and IL-6 and MPO activity compared with that of the S. aureus group." (PMID 36755021, 2023).